PER2 (period circadian regulator 2)
Diseases named in the same sentence as PER2 in open-access papers (continued):
Sharing a sentence is not in itself a finding about the gene and the disease.
cancer (continued). "Because PER1 and PER2 are involved in the DNA damage response pathways, abnormal expressions of them may result in cancer." (PMID 38892035, 2024). "Thus, DOPr can be a potential target for further study into the treatment of cancers related to the dysregulation of PER2." (PMID 38334624, 2024). "Pan-cancer single nucleotide variation analysis showed that the overall average mutation frequency ranged from 0 to 8.2%, and CRGs including AUTS2, TIMELESS, REV1, and PER2 showed high mutation frequencies." (PMID 36895015, 2023). "Per2 can inhibit the proliferation of a variety of cancer cells." (PMID 37069338, 2023). "Apparently, the divergent roles of PER2 in tumorigenesis depend on the cancer cell type or status." (PMID 37215573, 2023). "Since M47 decreases CRY1 and enhances the level of Per2 both in the cell line and in vivo, we hypothesized that M47 could be a useful molecule for cancer treatment by promoting apoptosis." (PMID 36347873, 2022). "The top intracellular pathways of the 12 overlapping genes were associated with circadian rhythms and entrainment (Arntl, Cry2, Per2, Per3, Bhlhe41), the cell cycle (Cdkn1a, Wee1), the oxytocin signaling pathway (Cdkn1a, Rcan1), and transcriptional misregulation in cancer (Cdkn1a, Per2)." (PMID 33668521, 2021). "Moreover, CART, SIRT1, and PER2 negatively correlated with the infiltration of M2 cells show good prognosis of cancer patients, while SERPINE1 and NFIL3 positively correlated with the infiltration of M2 cells show poor prognosis of cancer patients." (PMID 31927791, 2020). "Moreover, despite the expansive knowledge of Per1 and Per2 roles in cancer cells, their roles in the TME were largely overlooked." (PMID 33123539, 2020). "Low expressions of Per1 and Per2 could serve as unfavorable indicators for cancers prognosis, especially for gastrointestinal cancers." (PMID 32437452, 2020). "Most studies showed the resistant effect of PER2 in carcinogenesis, which might be similar in various types of cancers." (PMID 32185221, 2020). "Furthermore, the results revealed that low expressions of Per1 and Per2 were also correlated with poor overall survival of cancers (Per1: HR=1.35, 95%CI: 1.06∼1.72, P=0.014; Per2: HR=1.43, 95%CI: 1.10∼1.85, P=0.007)." (PMID 32437452, 2020). "Furthermore, hypermethylation of PER1/PER2/PER3 was observed in most cancers, although the hypermethylation of PER3 was only statistically significant in HNSC, BRCA, and THCA." (PMID 30791227, 2019). "We propose that miR-34a regulation of cancer progression could be partly explained via the PER2 gene as well." (PMID 31658284, 2019). "Per2 mutations in mice disrupt the clock and predispose mice to cancers, whereas disruption of the clock by Cry mutations (which also affects the negative transcription-translation feedback loop of circadian clock like Per2) does not increase cancer risk." (PMID 29100427, 2017). "The results suggest that blocking Per2 or HDAC1 may be a valuable remedy to prevent cancer metastasis." (PMID 26898709, 2016). "Per2 protein expression was silenced in combination with Dox in order to determine whether the chemoresistant MDA-MB-231 cancer cells can be sensitized to Dox treatment." (PMID 26347774, 2015). "In addition, Per1 and Per2 have been reported to be downregulated in several human cancers, and overexpression of either gene inhibits the growth of cancer cells." (PMID 25760074, 2015). "Additionally, the differences in Per2 protein expression patterns seen in different populations of the MDA-MB-231 cancer cells highlight the asynchronous nature of peripheral circadian clocks as well as the heterogeneity of cancer cell populations." (PMID 26347774, 2015). "We found that PER2 was significantly up-regulated in cancer tissues (p < 0.005)." (PMID 24708606, 2014). "Per1 and Per2 are relatively well characterized in terms of their roles in cancer." (PMID 23563360, 2013).
cancer (continued). "Moreover, functional studies found that overexpression of Per2 inhibited cancer cell growth in both culture system and xenograft mouse model." (PMID 22166120, 2011). "Consequently, these results indicate that DOPr, much like its role in wound healing, may also play a part in cancer development by influencing PER2." (PMID 38334624, 2024). "Per1−/− or Per2−/− mutations did not predispose mice to spontaneous and IR-induced cancers." (PMID 34375638, 2021). "Therefore, although heterogeneity existed, these pooled results suggested that low expressions of Per1, Per2, Per3 and Npas2 might play important roles in the development and progression of cancers." (PMID 32437452, 2020). "Indeed, mice carrying a point mutation of the PAS B domain of Per2 display a short period followed by arrhythmicity under DD, while mice lacking the domain entirely are prone to cancer." (PMID 22721557, 2012). "Co-citation networks bridged molecular chronobiology (Science, PNAS) and clinical oncology (Cancer Research), though mechanistic studies prioritized clock genes (e.g., BMAL1, PER2) over environmental disruptors." (PMID 40589644, 2025). "The key difference between the core clock in these cancers and healthy tissue was a significant delay in the peak expression times of core clock genes NR1D2, PER2, TEF and DEC1." (PMID 40424435, 2025). "While many cancer cell types continue to exhibit oscillations of the circadian clock, it was shown that deregulation of the key clock genes PER1, PER2, PER3, CRY1, CRY2, BMAL1, and CLOCK occurs in certain human malignancies." (PMID 38892035, 2024). "Emerging evidence suggests that alterations in clock genes, including the PER gene family (PER1, PER2, and PER3), play a significant role in cancer development and progression due to their regulatory functions in biological cycles and physiological processes." (PMID 38813085, 2024). "PER genes are deregulated at many levels in cancer, such as altered methylation of PER1 and PER2 promoter and increased expression, for example, in prostate cancer, as PER1 is regulated by androgen receptor signaling." (PMID 36731029, 2023). "As TIMELESS expression was significantly upregulated and RORA, PER1, PER2, and CRY2 expression was significantly downregulated in most cancer types including LUAD and LUSC, it is necessary to probe their prognostic values." (PMID 35078435, 2022). "The dysfunction of PER2 and PER3 has been related to cancer development and progression as well as poor prognosis in HNSC." (PMID 36505439, 2022). "We generated CC manipulated CRC cells (ARNTL, PER2 or NR1D1 knockout or knockdown) and compared clock (ARNTL-promoter activity) and cancer phenotype (proliferation, apoptosis and invasion) to that of MACC1 manipulated (knockout or overexpression) cells." (PMID 35884519, 2022). "A recent study using a cancer cell line model has also shown that CRY1 protein remains nuclear at all circadian phases and at markedly higher abundance than its partner protein PER2." (PMID 35285799, 2022). "GEPIA was used to understand the messenger (m)RNA expressions of circadian rhythm-related factors in the PER family (PER1, PER2, and PER3), CRY family (CRY1 and CRY2), BMAL1, and CLOCK in different types of cancer." (PMID 36385012, 2022). "Therefore, overexpression of PER2 may allow cancer cells to easily migrate and spread." (PMID 36385012, 2022). "In cancer, several CC genes, including CLOCK, ARNTL, PER2 and NR1D1 are dysregulated and play a role in tumourigenesis." (PMID 35884519, 2022). "According to findings on the function of Cry and Per2 in cancer, CRY destabilizers, which are predicted to be Per2 enhancers, can be used as novel anticancer therapies." (PMID 36347873, 2022).
cancer (continued). "PER1, PER2, and PER3 protein expression levels can be used as novel potential biomarkers for predicting cancer prognosis." (PMID 32849922, 2020). "Low expression of Per2 led to the activation of EMT genes TWIST1 and SLUG and promoted cancer metastasis." (PMID 32437452, 2020). "There were 4 studies with a total of 639 cases that assessed PER2 protein expression in the prognosis of cancer and 3 studies with a total of 393 cases that assessed PER3 protein expression in the prognosis of cancer." (PMID 32849922, 2020). "Of the 14 cancer types analyzed for gene expression, 11 types had downregulated PER1 expression, seven types had downregulated PER2 expression and 10 had downregulated PER3 expression." (PMID 33089179, 2019). "Numerous studies reported that individual molecular components of the circadian clock, such as BMAL1, PER2, or PER1 suppress proliferation or increase the sensitivity to anti-cancer drugs in different cancer cell lines." (PMID 28425940, 2017). "Our findings indicate BMAL1 as a readout of compromised PTEN and PER2 function and suggest that BMAL1 is involved in the progression of cancer." (PMID 27285754, 2016). "We demonstrated that in vitro and in vivo cancer cells after PER1 knockdown, PER2, DEC1, DEC2, CRY1, CRY2 and NPAS2 were significantly down-regulated at the mRNA level, while PER3, TIM, RORα and REV-ERBα were significantly up-regulated." (PMID 27602964, 2016). "proved that promoters of these clock genes (PER1, PER2, PER3, CRY1 and CRY2) were methylated in a variety of cancer cells, which resulted in their decreased expression." (PMID 27602964, 2016). "We showed that PER1, PER2, and PER3 gene expression levels were all lower in cancer tissue than in liver tissue, while CSNK1E gene expression was higher in cancer tissue." (PMID 27492458, 2016). "Compared with the normal tissues, the acrophases of Per2 and CDK1 were earlier in precancerous lesions, and the acrophases of Cyclin D1, CDK1 and Cyclin B1 occurred later in the cancer cells." (PMID 25950458, 2015). "Conversely, upregulating the PER2 gene in cervical cancer cells inhibited the PI3K/AKT pathway, diminishing multidrug resistance protein production and enhancing cisplatin’s lethal effect on cancer cells." (PMID 38813085, 2024). "In addition, there is a strong connection between Bmal1 and Per2 regulation and the PI3K/mTOR signaling pathway, one of the most frequently activated signaling pathways in tumorigenesis and the progression of cancer." (PMID 36768253, 2023). "For example, low PER1/PER2 expression in different types of cancer, such as breast, glioma, gastric and non-small cell lung cancer, is closely related to the development and metastasis of tumors." (PMID 36768253, 2023). "Collectively, these studies suggest that PER2 and PER3 are negative regulators of CSC physiology that could be potential targets for anti-CSC cancer therapy." (PMID 36430659, 2022). "In particular, PER2 KO cells showed the highest increase in cell invasion, possibly also due to a significant increase in MACC1 and a decrease in ECAD expression, leading to a more aggressive cancer phenotype by activating EMT markers." (PMID 35884519, 2022). "To test this hypothesis, we injected MC38 cancer cells (or PBS, as control) to the portal vein of Per2–/– and WT mice, harvested the livers 1 week following injection, and performed RNA-sequencing on total liver extracts." (PMID 33123539, 2020). "Cancer cell line MCF-7 with an ER-positive status treated with E2 had higher expression of PER2 than cell lines without ER." (PMID 29958276, 2018).
cancer (continued). "This study demonstrates that the down-regulation of PER1 in cancer cells can result in the robust up-regulation of PER3, TIM, RORα and REV-ERBα transcripts, while the expression of PER2, DEC1, DEC2, CRY1, CRY2 and NPAS2 is prominently down-regulated in vitro and in vivo." (PMID 27602964, 2016). "Quantitative real-time PCR result indicated that in vitro and in vivo cancer cells after PER1 knockdown, PER2, DEC1, DEC2, CRY1, CRY2 and NPAS2 were significantly down-regulated at the mRNA level, while PER3, TIM, RORα and REV-ERBα were significantly up-regulated." (PMID 27602964, 2016). "In contrast, the overexpression of Per2 inhibited proliferation and arrested cell cycling in cancer cell lines, thus supporting the negative growth-regulatory properties of Per2." (PMID 27494874, 2016). "They reported that PER2 was notably up-regulated in cancer tissues compared with noncancerous tissues." (PMID 26253128, 2015). "Once such ccg is cMyc, which is misregulated in the absence of Per2, and mice lacking Per2 expression are cancer prone." (PMID 25198253, 2014). "The PER1, PER2, and PER3 genes regulate cell growth, proliferation, and apoptosis, CRY1 and CRY2 regulate the transcription G1/S and G2/M cell cycle checkpoints, while BMAL1 and NPAS2 inhibit the proliferation and invasion of cancer cells by suppressing the c-Myc transcription factor." (PMID 36672355, 2023). "Adjusting Per2 gene expression without CR adjustment may be potential effective approach to reduce cell radiosensitivity such as reducing normal tissue injury in cancer patient radiotherapy." (PMID 36465103, 2022). "We also found AKT1-ARNTL positively correlated in HCT116 WT and SW480 control cells, whereas it was negatively correlated in ARNTL KO and PER2 KO in HCT116 and SW620 control cells, which might point to an alteration of clock regulation related to cancer progression." (PMID 35884519, 2022). "Finally, several SNPs in genes of the circadian rhythm unexplored with cognition previously were evaluated in cancer patients: rs1801260 in CLOCK (Circadian Locomotor Output Cycles Kaput), rs934945 in PER2 (Period circadian regulator 2), and rs10838524 CRY2 (Cryptochrome circadian regulator 2)." (PMID 36123640, 2022). "A negative correlation of PER2 and miR-34a was present only in patients with more advanced stages of CRC, which was consistent with miR-34a being preferentially associated with survival in patients at earlier cancer stages." (PMID 31658284, 2019). "In order to achieve a systematic understanding of circadian clock in cancer, we define a core subset of clock family genes including 7 positive regulators (CLOCK, NPAS2, ARNTL, ARNTL2, RORA, RORB, and RORC) and 7 negative regulators (PER1, PER2, PER3, CRY1, CRY2, NR1D1, and NR1D2)." (PMID 31708917, 2019). "Curcumin’s reported ability to prevent cancers may also be optimal at the time of day corresponding with this phase of highest sensitivity, which may be estimated from PER2 circadian rhythms measured in non-cancer cells of healthy individuals." (PMID 27680947, 2016). "On the contrary, lack of PER2 increases PI3K/AKT/mTOR signaling pathway, protein synthesis and cell proliferation and decreases autophagy in this type of cancer." (PMID 33042011, 2020). "Among 716 samples across 29 cancer types, we interestingly observe that most of the negative regulators, such as PER1, PER2, PER3, CRY1, CRY2, and NR1D2, are down-regulated in a wide range of cancers." (PMID 31708917, 2019). "Low expression of PER2 has been recognized as an independent prognostic variable in several cancers, including OSCC; however, the reasons for the reduced expression of PER2 in these cancers have not been fully determined." (PMID 40113747, 2025). "A significant negative correlation was also found between PER1/PER2 activity and VEGF expression in ESCC patients’ cancer tissue, showing that decreased levels of PER1/PER2 may influence VEGF levels." (PMID 31151182, 2019).
infection (15 papers, 2014 to 2024). The state of being infected such as from the introduction of a foreign agent such as serum, vaccine, antigenic substance or organism. "Only 5 cellular genes (Cyp1a1, Ltf, Nr4a3, Per2 and Zbtb16) were significantly modulated on day 1 post-infection." (PMID 35812400, 2022). "The expression of Ciart, Per2, Cilp2, Tnmd, Col2a1, and Wif1 at each time point post-infection was significantly different from that observed in uninfected diaphragms (P < 0.0001)." (PMID 33648561, 2021). "(G) Immunofluorescence of PER2 (red) at ZT12 in mouse SCN sections after infection with AAV (green) expressing scrambled shRNA, or shCdk5." (PMID 31687929, 2019). "The most active period of LPS-induced changes in SCN state seemed to occur about 8 hours after the infection; at this time, the Per2 was induced after the daytime LPS injection, compared to Nr1d1 after the night-time LPS injection." (PMID 30265676, 2018). "On the other hand, 60 days post-infection, the period of PER2::LUC expression in the SCN was shorter than in controls." (PMID 29302035, 2018). "We were able to confirm successful infection at the single-cell level using an adenovirus carrying Per2-luc." (PMID 28755004, 2017). "At a multiplicity of infection (moi) of 600 Ad-Per2 restored paraquat induced cytotoxicity in Per2Brdm1 mutant cells from 37.7 ± 2 (% cytotoxicity ± SEM) to 45.5 ± 3.1%, a level comparable to wild-type cells (43.9 ± 1.3%)." (PMID 25628599, 2014). "The infection efficiency of Per2 lentiviral vector was validated by fluorescence microscope." (PMID 35599595, 2022). "Indeed, we identified several core circadian genes, such as Per2 and Fbxl3, differentially regulated at various time points of infection, suggesting a direct role for regulating these clock genes intrinsically in CD8+ T cells." (PMID 35944008, 2022). "Six days post-infection, cell growth was significantly decreased in Per2-infected cells." (PMID 27346580, 2016). "In comparison to the proximal colon, the distal rectum is more susceptible to pathogen exposure, indicating that PER2 plays a unique role in defending rectal tissue against pathogen invasion, and the lack of Per2 renders the distal rectal tissue susceptible to pathogen infection." (PMID 37660913, 2023). "The daytime point of infection coincides with high levels of STAT3 protein and of clock genes Per1, Per2 and Nr1d1 mRNAs, and was chosen to deduce a possible LPS-induced decrease of their levels." (PMID 30265676, 2018). "Together, these results demonstrate that the sole presence of bacteria, in the absence of an infection, is sufficient to affect the expression of light-inducible (per2, cry1a) and non-inducible (per3, per1b) clock genes." (PMID 39537820, 2024). "We found a significant decrease of white colonies, but not red colonies, when Per2 is overexpressed with respect to GFP infection that was used as control (p < 0.05)." (PMID 32850472, 2020).
metabolic disorders (11 papers, 2013 to 2025). "Given that PER2 also interacts with nuclear receptors including PPARα and can regulate the expression of nuclear receptor target genes involved in lipid metabolism, PER2 polymorphisms could contribute to metabolic disorder vulnerability." (PMID 35276838, 2022). "Feeding only during the daytime in animals was also described to lead to metabolic disorders and disrupted rhythm in the expression of Per1 and Per2 mRNA in the perifornical area and the arcuate nucleus of the hypothalamus." (PMID 31139215, 2019). "In our study, the expression of both per2 and per3 were decreased in the WD group, and the expression of Bmal1 was increased, which may lead to disruption of circadian clock and metabolic disorder, and the disturbed expression of per2, per3 and Bmal1 were all rescued by fish oil feeding." (PMID 26832365, 2016). "Liver clock genes BMAL1 and PER2 are similarly reduced in animal models for both PCOS and NAFLD, emphasizing the commonality between these metabolic disorders." (PMID 39858445, 2025).